CCL5 (C-C motif chemokine ligand 5)
Diseases named in the same sentence as CCL5 in open-access papers (continued):
Sharing a sentence is not in itself a finding about the gene and the disease.
tumor (continued). "Further, inhibiting CCR5 through a novel antagonist targeting the CCL5/CCR5 axis suppresses tumor growth and metastasis in TNBC by regulating the CCR5-YAP1 signaling pathway, thereby disrupting pro-tumoral mechanisms." (PMID 40933989, 2025). "Our findings identify the CCL5/CCR5 axis as a key mediator of tumor-stromal crosstalk driving cisplatin resistance in NEPC." (PMID 41152972, 2025). "This CCL5-miR-199a-VEGF axis promotes endothelial cell migration and capillary tube formation, facilitating tumor-associated angiogenesis both in vitro and in vivo." (PMID 40429954, 2025). "Inflammatory chemokines, such as C–C motif ligand 5 (CCL5), regulate immune cell trafficking in the tumor microenvironment and control tumor progression, making them promising targets for cancer therapy." (PMID 40295404, 2025). "Upon activation, NK cells secrete IFN-β and CCL5, which further recruit additional immune cells to the tumor site." (PMID 41417876, 2025). "Real-time qPCR analysis of tumour tissues revealed that propionate treatment significantly upregulated the transcriptional levels of Meox1, Cxcr6, and Ccl5, whereas Meox1-siRNA administration abolished these effects." (PMID 40715695, 2025). "In tumors, cancer cell‐derived CCL2 and CCL5 usually contribute to the recruitment of MDSCs, TAMs, and Tregs to the tumor niche." (PMID 40105652, 2025). "ELISA analyses revealed that CXCL10 and CCL5 expression levels in tumor tissues were significantly lower in BIN1-KO mice compared to BIN1-WT mice." (PMID 40346580, 2025). "The CCL5/CCR5 axis promotes tumour progression via survival, proliferation, MMP activation, and immune suppression through Treg, MDSC, and TAM recruitment." (PMID 40361472, 2025). "Mechanistically, CCL5 binds to the CCR5 receptor on tumor cell surfaces, activating the downstream AKT signaling pathway, which cooperatively promotes AR and PD-L1 upregulation, ultimately driving CRPC progression and therapy resistance." (PMID 41154598, 2025). "Tumor-secreted CCL5 and CXCL8 also play roles in recruiting monocytes, neutrophils, and other leukocytes, which can differentiate into TAMs and tumor-associated neutrophils (TANs), both of which can assume pro-tumorigenic roles." (PMID 40365348, 2025). "On the other hand, by binding to the CCR5 receptor, CCL5 can recruit immunosuppressive cells such as TAMs and inhibit the function of tumor-specific T cells, thereby exacerbating tumor immune escape." (PMID 41376630, 2025). "Further research should focus on the specific mechanisms of CCL5 in recruiting immune cells and shaping the tumor immunosuppressive microenvironment." (PMID 40395456, 2025). "Re‐polarizing the tumor macrophages to T cell supporting phenotypes (secreting Ccl5, Cxcl9, and IL‐12) promotes T cell stimulation and adaptive immune recognition of tumors." (PMID 39639496, 2025). "Survival analysis of these genes in tumour samples identified seven genes that were associated with prognosis, including ACSL5, HSD17B11, CCL5, NCF2, PSME1, ACTB, and CYBB." (PMID 40299520, 2025). "RNA‐seq data of SYSUCC showed that the CCL5+ macrophage infiltration score was higher in pre‐therapy tumor tissues of responders compared with non‐responders in ESCC patients who received immunochemotherapy." (PMID 40995650, 2025). "Next, we tested the effects of the CCL5/CCR5 pathway on xenograft tumor growth via tumor-stromal interactions." (PMID 41152972, 2025). "In mice, elevated levels of CCL5 have further been shown to promote tumor immune evasion and mediate mesenchymal stromal cells homing into the TME, enhancing tumor growth." (PMID 40282185, 2025). "Once inside the tumor, OV-Cmab-CCL5 not only disrupted EGFR signaling, which is often upregulated in GBM, but also triggered a strong immune response." (PMID 40867316, 2025). "Elevated CCL5 expression is observed in various tumors and correlates with enhanced tumor growth and poor prognosis." (PMID 41445742, 2025).
tumor (continued). "For instance, intratumoral injection of E. coli MG1655 reprograms tumor‐associated macrophages toward a pro‐inflammatory phenotype producing CCL5, which enhances T‐cell infiltration and tumor clearance, suggesting that it can trigger TLS neogenesis." (PMID 40591148, 2025). "CCL5 is a pro‐tumorigenic chemokine that promotes tumor growth, metastasis, immune evasion, and angiogenesis by binding to CCR1, CCR3, and CCR5 receptors." (PMID 40356340, 2025). "These are all known factors that can enhance T cell‐mediated anti‐tumor immunity as Cxcl9 and Ccl5 are chemoattractive to T cells, and IL‐12 is a potent activator of CD8 T cell effector functions." (PMID 39639496, 2025). "We first investigated the effects of genetically targeting Ackr2 on the release by tumor cells of two chemokines, CCL5 and CXCL10, which can be scavenged by ACKR27 and have high affinity for this receptor." (PMID 40248897, 2025). "On the one hand, CCL5 enhances the anti-tumor immune response by promoting the recruitment of T cells and NK cells." (PMID 41376630, 2025). "CCL5 enhances GLUT1 expression on tumor cells, promoting glucose uptake and metabolic reprogramming to support proliferation." (PMID 40909271, 2025). "Mechanically, the tumor-derived CCL5 induced by L. intestinalis recruited DC chemotaxis through the NOD1/NF-κB signaling pathway." (PMID 39773173, 2025). "We further demonstrated that supplement of L. intestinalis increased the expression level of CCL5 in the tumor tissue of AOM/DSS-induced CRC model through ELISA and RT-qPCR." (PMID 39773173, 2025). "Together, these results demonstrate that cisplatin treatment effectively induces CCL5 expression in human and murine tumor samples." (PMID 41152972, 2025). "A study of a mouse glioblastoma model revealed that factors released by TAMs, notably CCL8, CCL5 and MMPs, contribute significantly to tumor invasion and growth through the breakdown of the extracellular matrix surrounding tissue." (PMID 41157253, 2025). "Overall, these findings demonstrate that tumor cell‐derived CCL5 is a key mediator of macrophage activation and lymphatic metastasis induced by LCN2 silencing in GC." (PMID 40884261, 2025). "Once recruited, CCL5 induces TAM polarization toward a pro-tumoral M2 phenotype that promotes tumor progression, immunosuppression, angiogenesis, and metastasis." (PMID 40868199, 2025). "DGE analysis revealed that liver Tregs, compared to tumor and PBMC Tregs, had higher expression of key genes linked to Treg recruitment and immune suppression (e.g., CXCR3, CCL3, CCL4, and CCL5)." (PMID 40848148, 2025). "Conversely, changes in the expression of CCL2, CCL5, and CCL21 were linked to tumor stages, influencing tumor growth and metastasis by modulating immune cell activity, thereby highlighting their value as therapeutic targets." (PMID 39859340, 2025). "This conclusion is also supported by a corresponding increase in the ligands for CXCR3, CCR5 (e.g., CXCL9, CXCL10, CCL5) in both tumor and liver supernatants after treatment, whereas CXCR6 ligand (CXCL16) is higher only in the tumor." (PMID 41415437, 2025). "KLF5 plays a role in stromal regulation of tumor progression via the CCL5/CCR5 axis, a tumor escape mechanism by instrumentalizing the immune cell compartment." (PMID 40465055, 2025). "The accumulation of suppressive cells can be reduced and anti-tumor immune responses can be enhanced by inhibiting CCL5/CCR5 binding." (PMID 41376630, 2025). "Tumor-conditioned LECs promote BC angiogenesis and direct its dissemination and proliferation via CCL5." (PMID 40248695, 2025). "Second, tumor‐homing eosinophils secrete chemokines such as CCL5, CXCL9, and CXCL10 that create chemotactic gradients for cytotoxic T lymphocytes." (PMID 41362643, 2025). "Through DEGs analysis, we observed that CD8+ TEF exhibited higher expression levels of CCL4 and CCL5, both of which facilitate the recruitment of macrophages, dendritic cells, and other T cells into the tumor microenvironment." (PMID 40303328, 2025).
tumor (continued). "In PAs/PitNETs, CXCL1 recruits macrophages and neutrophils, promoting tumor progression, and CCL5 enhances the tumor invasiveness." (PMID 40064752, 2025). "This metabolic disruption led to diminished CD8+ T cell recruitment to tumor sites, accompanied by reduced levels of Th1‐type chemokines CCL5 and CXCL10." (PMID 40672434, 2025). "Elevated CCL5 levels correlate with increased tumor burden following neoadjuvant chemotherapy, and gene expression profiling of residual tumors reveals enrichment of CCL5, suggesting its role in recruiting macrophages and fostering recurrence." (PMID 41142826, 2025). "These nanovesicles were found to reprogram tumor-associated macrophages by shifting their polarization from the pro-tumor M2 phenotype, thereby enhancing the secretion of chemokines CCL5 and CXCL9." (PMID 40867539, 2025). "Tumor cells secrete chemokines like CCL5, CCL7, and CXCL8, which recruit Treg cells and MDSCs into TME." (PMID 40672434, 2025). "This process, in turn, activates (neo-)antigen-specific CD8+ T cells, which migrate towards tumours, especially to CCL5-expressing tumours." (PMID 40650066, 2025). "Beyond macrophage recruitment, tumor-derived CCL5 also uses extracellular vesicles (EVs) to modify macrophage function, upregulating genes like OPN, SLPI, HGF, and NRG3, which promote invasion and metastasis." (PMID 40868199, 2025). "NicheNet indicated that tumor‐derived chemokines (CCL5, TGFB1) interacted with Tregs receptors (CCR4, CCR5, CXCR3), promoting the Treg recruitment." (PMID 41028931, 2025). "In a study conducted on rats with TNBC, it was observed that if CCL5 is blocked using antibodies can significantly reduce tumor metastasis, and it was also observed that the number of T cells and NK cells increased significantly." (PMID 40297849, 2025). "CCL5 expression is observed in T cells, platelets, macrophages, renal tubular epithelial cells, synovial fibroblasts, and tumor cells." (PMID 40070829, 2025). "In fact, in mesenchymal stromal cells (MSCs), a group of cells that play a crucial role in tumor metastasis, the expression of ISGs, such as the chemokine CCL5, is upregulated alongside the induction of cGAS-STING signaling." (PMID 40565309, 2025). "The relative RNA expression demonstrated that Ccl5, Ccl8, Cxcl9, Cxcl10, Cxcl13 and Ccl21 were significantly higher in the 4MOSC1 tumours following oHSV therapy." (PMID 39219056, 2025). "To further explore the mechanism involved in L. intestinalis activated CCL5 secretion in tumor cells, we performed KEGG enrichment analysis for the 253 up-regulated genes, revealing the top 10 enriched pathways." (PMID 39773173, 2025). "Nevertheless, while CCL5 became a more dominant ligand for CCR5 in the KPC-4545 tumor, CCL4 remained a dominant ligand for CCR5 and CXCL12, CXCL10, and CXCL16 arose as major ligands for different receptors in the KPC-3403 model following anti-IL-1β treatment." (PMID 39948655, 2025). "We observed that elevating tumor cell-derived CCL5 secretion was responsible for recruiting DC, consequently leading to a reduction in tumor growth." (PMID 39773173, 2025). "The hydrogel up-regulates IRF5 and down-regulates CCL5 secretion, which contributes to a significant increase in M1 phenotype macrophages, enhancing T-cell-mediated immunity and controlling tumor growth." (PMID 40420798, 2025). "For instance, CXCL9/10 secreted by DC1s establish chemotactic gradients that guide CXCR3+ CD8+ T cells to tumor niches, while their co-expression with CCL5 amplifies T cell infiltration and correlates with improved survival in solid tumors." (PMID 40698080, 2025). "Instead, it recruited a large number of CD4T_FOXP3+ regulatory T cells by highly expressing CCL5 and binding to the tumor chemokine CCR4 axis, forming a dense immunosuppressive “chemical barrier”." (PMID 40948762, 2025). "Overall, our results reveal that the effect of ITGβ8 on the crosstalk between tumor cells and macrophages occurs via the regulation of CCL5." (PMID 39535362, 2025).
tumor (continued). "Genetic ablation or pharmacological inhibition of DYRK1B changed the secretome of PDAC tumor cells to strongly attract macrophages into tumor sites via the overproduction of CCL5, CCL6, CXCL2, and MCSF." (PMID 39863750, 2025). "CCL5 is a key modulator of tumor growth and metastatic dissemination, and its receptor CCR5 is frequently overexpressed in TNBC." (PMID 41142826, 2025). "One key mechanism driving immunotherapy resistance involves the exclusion of cytotoxic T cells and NK cells from the tumor, due to the downregulation of important chemokines, such as CCL5, CXCL9, or CXCL1025–27." (PMID 40562773, 2025). "CCL5 then binds to CCR5 on tumor cells, activating the PI3K/AKT cascade and protecting these cells from cisplatin-induced cell death." (PMID 41152972, 2025). "Our study shows that in NEPC, CAF-derived CCL5 binds to CCR5 on tumor cells, activating the PI3K/AKT pathway to protect cells from DNA damage and cisplatin-induced cell death." (PMID 41152972, 2025). "A similar reduction of GZMB/CCL5-expressing CD4+ TILs was observed when a comparison was made between 1956 tumour-bearing WT mice and mice with a targeted disruption of the Lilrb4 gene." (PMID 39048822, 2024). "The mean tumor volume at the end of the monitoring time point was the lowest in the E. coli + OT-I T cells group, mirroring the critical role of both TAMs and CCL5 in mediating T cell infiltration for potentiating the antitumor immune response." (PMID 39572541, 2024). "Given the significant changes in CCL5 expression during combination therapy, we were intrigued about its effect on residual viable tumor cells." (PMID 39183447, 2024). "The upregulation of CCL5 expression in residual tumor tissue after treatment can be attributed to the increased release of CCL5 by CD8T cells stimulated by immunotherapy as well as the increased infiltration of CD8T cells into the TME caused by lenvatinib." (PMID 39183447, 2024). "In line with our findings, direct or indirect regulation of CCL5 had shown significant effects on mouse xenograft tumor size and metastasis." (PMID 39227943, 2024). "TIDC can produce chemokines (CCL2 and CCL3), cytokines (TNF-α and IL-6) and growth factors (VEGF and CCL5), which promote tumor angiogenesis and cancer cell proliferation as well as metastasis." (PMID 39470950, 2024). "CCL5 deficiency in KRAS mutant LUAD resulted in a decrease in Treg cells and reduced lung tumor burden, indicating that the production of CCL5 by tumor cells contributes to an immunosuppressive environment in the lung." (PMID 39114657, 2024). "The secretome testing on the cell supernatant of the SENP3 deletion group indicated down-regulation of the anti-tumor factors (CCL5 and IL-β) and up-regulation of tumor-promoting factors (IL-10 and TGF-β)." (PMID 39123188, 2024). "STING activation promotes the secretion of chemokines, such as CXCL9, CXCL10, and C-C motif chemokine ligand 5 (CCL5), establishing a chemical gradient that guides cytotoxic T lymphocytes (CTLs) into tumor tissue." (PMID 39834588, 2024). "Of relevance, conventional type 1 dendritic cell (cDC1) accumulation was shown to depend on NK-cell–derived CCL5 in mouse tumor models and their levels also correlated with patient survival in multiple cancer types." (PMID 39007345, 2024). "Tumor-secreted CCL5 can bind to CCR5 on macrophages, activating downstream STAT3 and AKT signaling pathways, which enhances the attraction of TAMs and promotes their polarization to the M2 phenotype." (PMID 39575419, 2024). "p38-MAX signaling in circulating tumor cells (CTCs) derived from HCC upregulates the expression of CCL5, while the expression of CCL5 recruits Tregs to facilitate CTC immune escape and metastatic seeding." (PMID 39000005, 2024). "The level of CCL5 is indirectly affected by the overexpression of PD-L1, and co-inhibition of both can reduce the recruitment of Tregs and increase the anti-tumor effect." (PMID 38590651, 2024).
tumor (continued). "CD4+ Th1-polarized effector memory cells expressing CXCR3 and CCR5, the receptors for CXCL9/10/11 and CCL5, respectively, are another significant component of tumor-infiltrating lymphocytes (TILs)." (PMID 39114657, 2024). "Amanda’s study showed that ITGAL promotes Cx3cr1 expression, cx3cl1-mediated migration and Ccl5 expression in microglia, thereby promoting microglial infiltration and tumor formation." (PMID 39605903, 2024). "TAMs-secreted CCL5 stabilizes tumor-expressed PD-L1, inhibiting the cytotoxic activity of T cells and inducing immune escape." (PMID 39114657, 2024). "CyTOF analysis showed that compared with the Ki67− counterparts, Ki67+ Tregs expressed higher levels of CCR4 and CCR5, receptors for the chemotactic factors CCL22 and CCL5 that are mainly produced by tumor cells, macrophages and DCs in the TME." (PMID 39438442, 2024). "Taken together, these results establish a paracrine circuit in which optic nerve neuronal injury results in glutamate release, oligodendrocyte IL-1β and TAM Ccl5 production, and tumor formation." (PMID 38308315, 2024). "This targeted modification increased NSCLC cell‐derived CCL5 secretion via CyPA‐CD147‐p38‐ZBTB32 signaling, which promoted NSCLC immunosuppression via CCL5/CCR5 axis‐dependent tumor cell‐macrophage crosstalk." (PMID 38873823, 2024). "CCL5 plays a role in physiological processes such as cell migration and immune response, and has a crucial role in anti-tumor activity." (PMID 39334887, 2024). "Regarding the underlying mechanism of the activation of tumor-infiltrating T cells, we observed that OBP-702 increased the release of CCL5 and CXCL10 from murine NHOS cells more strongly than OBP-301." (PMID 39108499, 2024). "b Protein extracted from Pa and LM4 tumor tissues was used to compare CCL5 expression levels within each tumor by ELISA." (PMID 39126553, 2024). "Several NKRGs, like CCL5, demonstrate dual effects on tumors by promoting both tumor progression and enhancing anti-tumor immune responses." (PMID 39507529, 2024). "According to multivariate Cox regression analysis (adjusted for tumor stage, lymph node stage, chemotherapy, and molecular subtype), CCL5 positivity appeared to be an independent poor prognostic factor only for DSS (RR = 1.51; p = 0.047)." (PMID 38928033, 2024). "Optimized doses of the HDAC inhibitor Tucidinostat significantly polarized M2-like to M1-like macrophages in three mouse tumor models by activating the NF-B signaling pathway and upregulating CCL5." (PMID 38341519, 2024). "Research indicates that BJJP inhibits tumor cell growth in an immune-dependent manner, modulating CCL5 expression and promoting CD8+ T cell infiltration into HCC tumors in H22 tumor-bearing mice." (PMID 39206194, 2024). "A clinical study on MIBC revealed distinct prognostic outcomes based on the expression of CCL5 in tumor cells versus infiltrating immune cells." (PMID 39409924, 2024). "In cancer, tumor and stromal cells secrete CCL5, which promotes tumor progression and chemoresistance by interacting with its receptor, CCR5, found on various immune cells." (PMID 39261943, 2024). "Compared to sporadic PitNETs, familial PitNETs exhibit higher expression of CCL5 in tumor tissues with abundant infiltration of macrophages." (PMID 38716256, 2024). "CCL5 exhibits late expression following T cell activation and localizes with tumor-infiltrating leukocytes." (PMID 39199626, 2024). "Because mouse CCR5 differs significantly from human CCR5 30, it cannot function as a chemoattractant receptor for CCL5; thus, xenograft tumour model was insufficient to permit the entry of monocytes into the tumour for differentiation to TAM." (PMID 39267775, 2024). "In mouse models of estrogen receptor-positive breast cancer (ER+ BC), the use of neutralizing antibodies against CCL5 significantly reduced macrophage infiltration and decreased tumor volume." (PMID 39575419, 2024).